CAV1 (caveolin 1)
Diseases named in the same sentence as CAV1 in open-access papers (continued):
Sharing a sentence is not in itself a finding about the gene and the disease.
prostate carcinoma (continued). "We previously developed a similar assay to detect and quantify plasma exosomes expressing Rab5B/CD63 or Rab5B/caveolin plasma exosomes and demonstrated that CD63+ exosomes or caveolin-1+ exosomes were significantly increased in melanoma and prostate cancer patients as compared to healthy donors." (PMID 32231660, 2020). "In contrast, mRNA expression of enzymes involved in the biosynthesis of glycosphingolipids, including glucosylceramide synthase (UCGC), and lactosylceramide synthases B4GALT5 and B4GALT6, were elevated in CAV1-high prostate cancer cell lines and prostate tumors." (PMID 32855410, 2020). "CAV1-containing conditioned media (CM) from high passage CAV1-secreting, human prostate cancer LNCaP (LNCaPCAV1) cells augmented viability and clonal growth of low passage, CAV1-negative, LNCaP cells in vitro, and addition of CAV1-specific antibodies to the CM blocked this effect." (PMID 31362353, 2019). "Moreover, intraperitoneal injections of mice with these CAV1-specific antibodies suppressed the orthotopic growth and spontaneous metastasis of highly metastatic, CAV1-secreting mouse prostate cancer cells in vivo." (PMID 31362353, 2019). "Additionally, in this regard, the presence of other scaffolding proteins, such as flotillin-1, have been reported to modulate the sorting of CAV1 into exosomes in PC3 prostate cancer cells." (PMID 31362353, 2019). "Consequently, the inhibition of caveolin-1 neddylation stimulated the migration of prostate cancer and glioblastoma cells." (PMID 29301501, 2018). "Therefore, prostate cancer is closely related to caveolin-1 since prostate cancer of a high pathological grade was often accompanied by the high expression of caveolin-1." (PMID 30424755, 2018). "As we showed that ITGB1 is an upstream regulator of CAV1 expression and the two proteins are correlated in vitro, we asked if this correlation could be validated in a large clinical prostate cancer cohort." (PMID 29402961, 2018). "We developed a computational pipeline and applied it to analyzing 3D point clouds of SMLM localizations (event lists) of the caveolar coat protein, caveolin-1 (Cav1), in prostate cancer cells differentially expressing CAVIN1 (also known as PTRF), that is also required for caveolae formation." (PMID 29899348, 2018). "Recent studies have proved that caveolin-1 is associated with the incidence and progression of prostate cancer, but the specific mechanism is not clear." (PMID 30424755, 2018). "The expression of caveolin-1 was significantly higher in prostate cancer samples than in benign prostatic hyperplasia samples (P < 0.05), and caveolin-1 expression was significantly different among the pathological grades of poorly, moderately and well-differentiated prostate cancer (P < 0.05)." (PMID 30424755, 2018). "After subtracting mRNA expression levels of non-malignant specimens from human prostate cancer specimens, caveolin-1 and beta-catenin mRNA expression levels were significantly higher in African-American prostate cancer patient specimens compared to Caucasian-American prostate cancer specimens." (PMID 28697756, 2017). "However up to now a detailed mechanism how Cav1(−) HS5 fibroblasts foster Cav1 upregulations or (re) expressions in malignant prostate cancer cells and thereby radiation resistance remains elusive." (PMID 28112237, 2017). "Our results indicate that the expression of beta-catenin and caveolin-1 may be prostate cancer- and race-specific." (PMID 28697756, 2017). "Moreover, ER stress reduces Cav112 and overexpression of Cav1 mitigates ER stress in prostate cancer cells." (PMID 28181559, 2017). "Based on data from both human prostate cell lines and limited patient specimens, our results indicate that differential expression of caveolin-1 and beta-catenin may be race- and prostate cancer-specific." (PMID 28697756, 2017). "In advanced prostate cancer, an absence of stromal Cav-1 was associated with metastatic disease and epithelial AKT activation." (PMID 28546853, 2017).
prostate carcinoma (continued). "Caveolin-1 could possibly become a useful prognostic marker for prostate cancer patients that are potential candidates for active surveillance." (PMID 27764093, 2016). "Moreover, we demonstrate that endothelial Cav1 is a critical regulator of microvascular sensitivity to ionizing radiation in MPR31-4 prostate cancer xenograft tumors with impact on tumor growth delay after local irradiation." (PMID 25985209, 2015). "Further studies are needed to address the role of Cav1 for radiosensitivity of prostate cancer epithelial cells and to develop and validate the use of pharmacological strategies to reduce Cav1 expression or inhibit resistance-promoting Cav1-dependent signals, respectively." (PMID 25985209, 2015). "Our clinical findings were not in agreement with those reported from breast and prostate cancer patients, where the absence of CAV1 in the TME was associated with advanced stage, recurrent disease, metastatic spread and poor survival." (PMID 25633184, 2015). "Specific exosomal transport of CAV1 has been shown in only a few systems thus far, and it included exosomes in the plasma of melanoma patients and in the vesicular organelles (prostasomes) secreted by human prostate cancer cells." (PMID 25633184, 2015). "This suggests that Cav1 regulates various aspects of prostate cancer progression that contribute to treatment failure and may therefore constitute a valuable therapeutic target." (PMID 25985209, 2015). "Moreover, we show that knockdown of IQGAP1 or caveolin-1 in PC-3 cells abolished the hypercholesterolemia-induced metastasis from xenografts, indicative of their functional involvement in prostate cancer metastasis in vivo." (PMID 25924234, 2015). "and the cholesterol-binding membrane protein, caveolin-1, in promoting prostate cancer progression." (PMID 25924234, 2015). "Cav-1 can be secreted by prostate cancer cells and displays paracrine and endocrine functions." (PMID 26328273, 2015). "In addition, secreted CAV1 detected in serum from patients with prostate cancer is now being considered as a novel target for treatment." (PMID 24500501, 2014). "A substantial number of detailed analyses suggest that caveolin-1 may enhance cell survival and migration, notably in prostate cancer cells." (PMID 25397596, 2014). "Caveolin-1 is, therefore, a biomarker and therapeutic target for prostate carcinomas." (PMID 24932304, 2014). "Our recent studies showed that Cavin-1 expression in prostate cancer cells that express endogenous CAV1-modulated secretion pathways and cholesterol distribution, with decreased levels of cholesterol and impaired recruitment of actin to the detergent resistant membranes." (PMID 24714042, 2014). "Indeed, injection of anti-CAV1 antibodies reduced experimental lung metastasis in a mouse model of prostate cancer." (PMID 24500501, 2014). "It is intriguing to speculate that CAV1 expression may not only follow a pattern similar to that described for prostate cancer but also promotes metastasis by similar mechanisms." (PMID 24500501, 2014). "A hypothesis put forward to explain the role of PTRF in prostate cancer has been the potential for PTRF to trap caveolin-1 in caveolae and thereby reduce its secretion." (PMID 24123650, 2013). "For example, in breast and prostate cancer, loss of stromal Cav-1 but not tumor cells Cav-1 heralds poor prognosis, indicating the compartment-dependent roles of Cav-1." (PMID 23527097, 2013). "However, despite elevated caveolin-1, prostate cancer cells in clinical samples lack PTRF expression." (PMID 24123650, 2013). "We conclude that the overexpression of cav-1 and cholesterol overload in aggressive prostate cancer cell lines, suggests that cav-1 may confer survival advantage on prostate cancer cells leading to disease progression." (PMID 23934233, 2013). "Caveolin-1 (Cav-1) is an integral membrane protein that is overexpressed in prostate cancer cells." (PMID 24213111, 2011).
prostate carcinoma (continued). "However, Cav-1 serum levels in patients with prostate cancer have been shown to be a potential biomarker in this disease." (PMID 22040717, 2011). "Our results confirm data from earlier studies that were obtained in breast, lung, and prostate cancer cell lines, in that high expression levels of caveolin-1, caveolin-2, annexin-1, moesin, Eph2A, and uPA were associated with in vitro sensitivity to dasatinib." (PMID 19861960, 2009). "Indeed, it has been recently reported that prostasomes (membrane vesicles secreted by prostate cancer cells) contain caveolin-1 (Cav1), a major component of caveolae and that serum level of Cav1 is elevated in prostate cancer patients." (PMID 19381331, 2009). "However, in a significant number of tumour entities including carcinoma of the pancreas, squamous cell carcinoma of the lung, renal cell carcinoma, and carcinoma of the prostate, overexpression of Caveolin-1 has been described." (PMID 17915016, 2007). "Indeed within prostate cancer cell lines, caveolin-1 has been shown to be secreted in response to androgens and glucocorticoids." (PMID 14612902, 2003). "Except for the case of prostate cancer, however, the molecular and cellular underpinnings of the relationship between caveolin-1 expression and cancer progression remain unclear." (PMID 12402154, 2002). "Caveolin-1 was recently identified as a metastasis-related gene in prostate cancer." (PMID 12402154, 2002). "Therefore, baicalein may inhibit the occurrence and development of androgen-independent prostate cancer through the Cav1/AKT/mTOR pathway." (PMID 37910338, 2023). "Moreover, in prostate cancer, it was found that genomic amplification in the region Ch 7q31-36 could result in downregulating CAV1, while overexpressing EZH2." (PMID 36471782, 2022). "CAV1 in prostate cancer could induce epithelial–mesenchymal transition through activating cancer immune evasion, and CAV1 in cancer-derived exosomes was able to induce chemoresistance in recipient cells, which conformed to our results revealed in GEM-resistant BCa." (PMID 35127724, 2021). "Concurrently, a loss of stromal CAV1, particularly affecting cancer associated fibroblasts (CAF), could be observed, which correlated with tumor progression, therapy resistance, and predicted adverse outcome, e.g. in breast and prostate cancer." (PMID 33868995, 2021). "Caveolin-1 is closely related to the pathological grade and clinical stage of prostate cancer after transurethral surgery, and it may be a novel tumor marker for prostate cancer." (PMID 30424755, 2018). "To investigate whether reduced Cav1 expressions might alter the radiation response of malignant prostate epithelial cells we performed in vitro experiments using the human prostate carcinoma cell line PC3 in combination with shRNA knock-down of Cav1 expression." (PMID 28112237, 2017). "Therefore, the reduction of caveolin-1 protein levels and the increased protein levels of beta-catenin seen in the tumorigenic RC-77 T/E cells were mirrored in the downregulation of caveolin-1 mRNA and upregulation of beta-catenin mRNA in African-American prostate cancer specimens." (PMID 28697756, 2017). "Thus, Cav1 might be a promising therapeutic target for combinatorial therapies to counteract radiation resistance of prostate cancer at the level of the tumor vasculature." (PMID 25985209, 2015). "Thus, expression of CAV1 may be lost in the early stages of prostate cancer and promote cancer cell proliferation and survival, but up-regulated at late stages of prostate cancer to favor metastasis, inhibit apoptosis and promote multi-drug resistance." (PMID 26112043, 2015).
prostate carcinoma (continued). "Consequently lowering Cav1 levels in tumor ECs may be suited to improve the outcome of radiation therapy in prostate cancer." (PMID 25985209, 2015). "Alternatively, an attractive secreted protein that could mediate the effect of PTRF on angiogenesis is caveolin-1, which is increased in the serum of prostate cancer patients, has been shown to exert paracrine proangiogenic effects, and can be antagonized by caveolin-1 antibody." (PMID 24123650, 2013). "Also, from the GAD DAS annotation, we know that CAV1 and CAV2 are associated with prostate cancer." (PMID 19919683, 2009). "Importantly, recent results have revealed a potential therapeutic relevance of Caveolin-1 since the Caveolin-1-promoter has been hypothesized to be used as a specific target in gene therapy of prostate carcinoma in the nearer future." (PMID 17915016, 2007). "While being downregulated in early stage malignancies and thereby mediating growth promoting effects, upregulation of Caveolin-1 in late stage disease might promote resistance against chemotherapeutic agents in colon cancer as well as metastatic properties in prostate cancer." (PMID 17915016, 2007). "In prostate cancer, PTRF expression was lost, and the levels of OT became diminished, removing this regulation over caveolin alongside a consequential upregulation of cav-1 and particularly cav-2 expression." (PMID 39857963, 2025). "The expression levels of CAV1, PALLD, ITGB8, and CLDN7 were analyzed using RT-qPCR in the normal prostate epithelial cell line RWPE1 and four prostate cancer cell lines: LNCaP, 22RV1, DU145, and PC3." (PMID 40002724, 2025). "The major objective of this study was to develop a novel bioactive cell-penetrating peptide (bioportide), which, by mimicking the PP1-binding motif of caveolin-1 (CAV1), would regulate PP1 activity, to hinder prostate cancer (PCa) progression." (PMID 39339236, 2024). "More recently, a molecular and functional link between PrPC and caveolin 1 (CAV1), the protein coat of caveolar plasma membrane identified as marker of EMT, has been reported in human PC3 prostate cancer cells, LoVo and MDST8 colon cancer cell lines." (PMID 37452879, 2023). "Patients with positive family history for prostate cancer showed high levels of EGFR, TG, TC, LDL, alkaline phosphatase (ALP), but low AKR1C4, SLDLRP1, CAV1 and ABCA-1 levels." (PMID 36480560, 2022). "Among the significant analyses, 70% of the study revealed that CAV1 and CAV2 were all significantly downregulated in most tumor types, especially in BC, lung cancer, ovarian cancer, prostate cancer, bladder cancer, and sarcoma cancer." (PMID 36147736, 2022). "The detection of CAV1 and CAV2 in urine can be used to distinguish between CRPC and non-CRPC, and 12 urinary peptides have been found to be able to distinguish between prostate cancer and benign conditions." (PMID 34576294, 2021). "We considered the implications of our findings of this adaptive Cav-1-mediated glycosphingolipid mechanism and developed the hypothesis that targeting of the ceramide to glycosphingolipid conversion may represent an actionable metabolic vulnerability in prostate cancer." (PMID 32855410, 2020). "In this context relevant, CAV1 and CD59 are present together with delta-catenin in urinary EVs of prostate cancer patients, whereby delta-catenin was shown to be released to the extracellular matrix thanks to the presence of CAV1 and CD59." (PMID 31362353, 2019). "We demonstrated that there is increasing Cav-1, ACC1 and FASN expression during prostate cancer progression (P<0.0001, P=0.007 or P<0.0001 respectively based on Fisher's exact test)." (PMID 27331874, 2016). "However, in later stages of prostate cancer, expression and formation of Mgat5/galectin-3 lattices may stimulate and elevate the expression of CAV1 through phosphorylation, resulting in up-regulated CAV1 expression in advanced prostate tumours." (PMID 26112043, 2015).
prostate carcinoma (continued). "At the same time, CAV1 is considered a general tumor suppressor, the lack of expression of which was implicated in the pathogenesis of many cancers, while the over expression of which has also been associated with tumor progression and metastasis in prostate cancers." (PMID 25915206, 2015). "In agreement with a role in mediating metastasis, the level of IQGAP1 is higher in aggressive prostate cancer cells, PC-3 and DU145, which also express caveolin-1." (PMID 25924234, 2015). "This unusual imbalance between Cav-1 and PTRF expression is exemplified in the prostate cancer cell line PC3." (PMID 24123650, 2013). "In agreement with studies performed in prostate cancer cells, introduction of a dominant negative form of EphA2 into TC71 and RDES recapitulated most of the effects induced by CAV1 silencing." (PMID 23951165, 2013). "We have previously reported that exogenous expression of PTRF/cavin-1 in the prostate cancer cell line PC3, which expresses abundant caveolin-1 but lacks PTRF/cavin-1, significantly reduced transmigration on collagen-coated polycarbonate filters." (PMID 22912783, 2012). "Although there is no direct literature showing that caveolin-1 can affect the release of exosomes by regulating EE generation, there is literature showing that caveolin-1 can be released through exosomes in prostate cancer cells." (PMID 40659888, 2025). "Moreover, the combination of TPL and Cav-1 knockdown enhances the anti-migration and anti-invasion effects of TPL on prostate cancer cells." (PMID 40599799, 2025). "Therefore, during the evaluation of the effect of AOH on prostate cells’ steroidogenesis, we also decided to evaluate the possible changes in CAV-1 expression and localization, due to the known role of CAV-1 in prostate cancer." (PMID 37298472, 2023). "Since scRNA-seq analysis revealed that αSMA+ CAV1+ and FN1+ FAP+ CAFs were the two most abundant subpopulations of CAFs in prostate cancer microenvironment, we thus stained prostate cancer samples with these four fibroblasts markers to verified our findings from the bioinformatic analysis." (PMID 37033924, 2023). "CAV1 also interacts with the low-density lipoprotein receptor protein 6 (LRP6) and stimulates the kinase activities of the insulin and IGF-I receptors (IGF-IR/IR) in PC-3 cells, as well as in primary human prostate cancer tumors and metastases." (PMID 35740528, 2022). "Yet to our knowledge, and following exploration of the TCGA PanCancer Atlas dataset available via cBioportal, an altered expression of AKT1, CAV1, THBS1, or TIMP2 has not been previously associated with progression to aggressive prostate cancer." (PMID 34596356, 2021). "While these proteins are co‐expressed in healthy human cells, advanced prostate cancer cells express CAV1 without CAVIN1, leading to aberrant pro‐metastatic non‐caveolar CAV1 domains." (PMID 33931969, 2021). "To determine if CAVIN1 directly influences hnRNPK localisation or acts by neutralizing non‐caveolar CAV1, we ectopically expressed CAV1 in two cell lines that naturally lack CAV1 and CAVIN1, namely the androgen‐sensitive prostate cancer cell line LNCaP, and human embryonic kidney HEK293 cells." (PMID 33931969, 2021). "Furthermore, some studies have suggested a role for caveolin-1 (Cav-1), a protein of lipid rafts, in the regulation of the VEGF-R pathway in prostate cancer and endothelial cells." (PMID 34205419, 2021). "A set of transcripts including Caveolin‐1 (CAV1), TMP2, THBS1, and CTGF were found to be successful in discriminating clinically insignificant (Gleason = 6) disease from clinically significant (Gleason > 8) prostate cancer." (PMID 34596356, 2021). "Consistent with our previous report, assessment of conditioned media (CM) confirmed detectable levels of Cav-1 in CM from PC-3M and RM-9 prostate cancer cell lines but not LNCaP." (PMID 32855410, 2020).